PTX3 (pentraxin 3)
Diseases named in the same sentence as PTX3 in open-access papers (continued):
Sharing a sentence is not in itself a finding about the gene and the disease.
cervical cancer (19 papers, 2016 to 2025). A primary or metastatic malignant neoplasm involving the cervix. "Then, we conducted this study to explore the relationships between PTX3 genetic variants and the development of cervical cancer and patient survival." (PMID 33967610, 2021). "In univariate analysis, PTX3 genetic variants rs2120243 and rs1840680 had nothing to do with 5 years survival in cervical cancer patients (HR: 0.62, 95% CI: 0.24-1.59, p=0.318 for rs2120243; HR: 0.76, 95% CI: 0.31-1.89, p=0.556 for rs1840680)." (PMID 33967610, 2021). "We further investigated the relationships between PTX3 genetic variants and clinopathological parameters of cervical cancer." (PMID 33967610, 2021). "Recent evidence has suggested that the positive expression of matrix metalloproteinase-2 (MMP-2) and matrix metalloproteinase-9 (MMP-9) was associated with PTX3 expression in the regulation of human cervical cancer cell metastasis." (PMID 28489600, 2017). "In our study, we demonstrated that the overexpression of PTX3 in cervical cancer tissues was significantly associated with tumor grade and tumor differentiation." (PMID 27377307, 2016). "In another study, miR-224 was found to be associated with PTX3 expression in cervical cancer." (PMID 41479916, 2025). "Moreover, PTX-3 decreased plasmatic levels have been associated with suppression of metastatic potential of cervical cancer cells and lower possibility of HPV infection to evolve to dysplasia." (PMID 36499628, 2022). "Thus, we designed this study to investigate the significance of PTX3 genetic variants in the occurrence of cervical cancer." (PMID 33967610, 2021). "Furthermore, the association between PTX3 expression and clinicpathological parameters was analyzed in 60 cervical cancer patients." (PMID 27377307, 2016). "Notably, PTX3 is also considered a potential innovative diagnostic biomarker for cervical cancer." (PMID 41479916, 2025). "A panel of 11 plasma proteins, including PTX3, can differentiate cervical cancer patients from healthy controls with high sensitivity and specificity." (PMID 41479916, 2025). "PTX3 is highly expressed in human cervical cancers, and contributes to tumorigenesis and metastasis of cervical cancer cells." (PMID 41479916, 2025). "The overexpressed miR-224 promotes the proliferation, migration, and invasion of cervical cancer cells by suppressing its downstream target PTX3." (PMID 41479916, 2025). "In human cervical cancer cells, PTX3 knockdown has been shown to inhibit tumorigenicity and metastasis, particularly lung metastasis." (PMID 41479916, 2025). "According to their findings, miR-224 is overexpressed while PTX3 expression is reduced, promoting cell proliferation, migration, and invasion in cervical carcinoma." (PMID 41479916, 2025). "In vitro studies of cervical cancer revealed a correlation between the expression of PTX3 and the differentiation of this cancer." (PMID 36290747, 2022). "For example, in cervical cancer, inhibition of miR-224-5p prevents disease progression by targeting PTX3." (PMID 35739102, 2022). "In female reproductive system tumors, PTX3 was found to be overexpressed in cervical cancer, which was related to tumor grade and differentiation." (PMID 33952272, 2021). "Evidence also suggests that PTX3 promotes metastasis of cervical cancer and EGF-induced metastasis of HNSCC through upregulation of MMP-2 and MMP-9." (PMID 34917682, 2021). "Silencing PTX3 demonstrated a significant inhibition of the malignant biological behavior of cervical cancer cells." (PMID 33952272, 2021). "The depletion of PTX3 inhibited EGF-induced MMP-9, which was consistent with the association between MMP-9 and PTX3 expression observed in cervical cancer cell metastasis." (PMID 28489600, 2017). "We further confirmed that PTX3 inhibited the growth and metastasis of cervical cancer cells in vitro and in vivo, suggesting the tumor promoter role of PTX3 in cervical cancer." (PMID 27377307, 2016).
cervical cancer (continued). "Further studies are warranted to demonstrate PTX3 as a novel therapeutic biomarker for human cervical cancer." (PMID 27377307, 2016). "In this study, we demonstrated that the knockdown of PTX3 suppressed the metastatic ability of cervical cancer cells, which is consistent with the previous notion that PTX3 is a potential therapeutic target for head and neck cancer." (PMID 27377307, 2016). "In this study, we further investigate the clinical significance and biological function of PTX3 in cervical cancer cells in vitro and in vivo." (PMID 27377307, 2016). "Next, we inhibited the endogenous expression of PTX3 in HeLa and SiHa cells by shRNA assay to further investigate the biological function of PTX3 on human cervical cancer cells." (PMID 27377307, 2016). "Our results demonstrated that PTX3 contributes to tumorigenesis and metastasis of human cervical cancer cells." (PMID 27377307, 2016). "Our results support the implication that the oncogenic role of PTX3 is related to its promoter action on proliferation, which sets the basis for the identification of a PTX3 promoter that is essential for cervical cancer progression." (PMID 27377307, 2016). "Further investigations are warranted to elucidate the molecular mechanism of PTX3 in the metastasis of cervical cancer cells." (PMID 27377307, 2016). "This study focused on the biological function of PTX3 in proliferative and invasive human cervical cancer." (PMID 27377307, 2016). "Given that the exact role of PTX3 in cervical cancer remains unclear, further research focusing on PTX3’s interactions with signaling pathways, microRNAs, and other molecular components is necessary." (PMID 41479916, 2025). "Similarly, in cervical cancer cell lines, PTX3 knockdown resulted in reduced expression of key molecules involved in tumor cell migration and invasion, including MMP2, MMP9, and urokinase." (PMID 39594709, 2024). "To date, no study investigates the involvement of PTX3 genetic variants in the development of cervical cancer and patient prognosis in Taiwanese women." (PMID 33967610, 2021). "So far, there have been no studies linking PTX3 genetic variants to cervical cancer tin Taiwanese women." (PMID 33967610, 2021). "Overexpresssion of miRNA-224 and silencing or under expression of PTX3 was related to aggressive progression of cervical cancers.These observations may facilitate the development of potential therapeutic agents against cervical cancer in future." (PMID 33906290, 2021). "In addition, it has been found that PTX3 contributes to carcinogenesis and metastasis of human cervical cancer cells and regarded as a possible biomarker for cervical cancer." (PMID 33967610, 2021). "However, the expression of PTX3 promotes cervical cancer metastasis and EGF-induced HNSCC metastasis via the up-regulation of MMP-2 and MMP-9." (PMID 28489600, 2017). "PTX3 expression was higher in cervical cancer tissues compared with normal cervical tissues." (PMID 27377307, 2016). "Collectively, these results suggested that knockdown of PTX3 could inhibit cervical cancer cell proliferation." (PMID 27377307, 2016). "Furthermore, knockdown of PTX3 significantly decreased the potential of migration and invasion of cervical cancer cells by inhibiting matrix metalloproteidase-2 (MMP-2), MMP-9, and urokinase plasminogen activator (uPA)." (PMID 27377307, 2016). "Upregulating PTX3 by inhibiting miR-224 may help protect against cervical cancer development." (PMID 41479916, 2025). "Moreover, after controlling the clinicopathological parameters through multivariate analysis, we also found that PTX3 genetic variants had no significant influence on 5 years survival in cervical cancer patients." (PMID 33967610, 2021). "Furthermore, overexpression of PTX3 could promote the proliferation and invasion of cervical cancer in vitro and in vivo." (PMID 31334115, 2019).
cervical cancer (continued). "Additionally, PTX3 may be a tumorigenic agent that modulates tumor growth promotion and metastasis of cervical cancer in vitro and in vivo." (PMID 27377307, 2016). "However, the role of PTX3 in cervical cancer and the mechanism responsible for the oncogenic roles of PTX3 remain unknown." (PMID 27377307, 2016). "PTX3 may serve as a potential therapeutic target for the treatment of cervical cancer." (PMID 27377307, 2016). "Pentraxin 3 (PTX3), a molecule involved in MMP expression, is a component of innate immunity whose knockdown inhibits MMP-2 and MMP-9, decreasing migration and invasion of cervical cancer cells in vitro and in vivo." (PMID 32455616, 2020). "In addition, PTX3 was strongly expressed in grade 2 or grade 3 cervical cancer tissues on tissue microarray (TMA); however, PTX3 was weakly expressed in grade 1 cervical cancer tissues." (PMID 27377307, 2016). "However, the effects of PTX3 on the biological features of cervical cancer cells in vitro and in vivo have not been delineated." (PMID 27377307, 2016).
gastric cancer (18 papers, 2016 to 2025). A primary or metastatic malignant neoplasm involving the stomach. "Similar findings were found in a gastric cancer cell study in which inhibition of the PTX3 gene suppressed cancer-associated inflammation through inhibition of the migration of macrophages." (PMID 39594709, 2024). "Other studies have also shown that the expression of PTX3 is elevated in gastric cancer tissues and induces tumor-associated gastritis by increasing the migration of macrophages and neoplastic cells." (PMID 36290747, 2022). "These divergent findings suggest that the impact of PTX3 on gastric cancer may depend on the underlying molecular mechanisms and the characteristics of different cell lines, necessitating further research to clarify its precise role in this context." (PMID 41479916, 2025). "On the other hand, due to multiple associations between PTX-3 and gastric cancer progression through inflammatory pathways, PTX-3 could rather be considered a tumor promotor instead of tumor suppressor, especially in advanced stages or metastasis of gastric cancer." (PMID 36499628, 2022). "PTX3 is less expressed in gastric cancer, but overexpression of PTX3 inhibits gastric cancer cell migration, invasion, and EMT, which can be reversed by TNF-α treatment." (PMID 41479916, 2025). "PTX3 expression is elevated in advanced gastric cancer samples via TNF-α/NF-κB activation, thus promoting cancer cell migration and the recruitment of macrophages." (PMID 41479916, 2025). "The migration-promoting effect of PTX3 in bone-metastatic gastric cancer cells aligns with another study that demonstrated PTX3 upregulation via the BDNF/TrkB axis, enhancing gastric cancer-osteoblastic niche interactions and contributing to bone metastasis." (PMID 41479916, 2025). "For example, in vitro experiments have shown that exposing gastric cancer cells to TNF-α enhances their invasive potential by downregulating protective factors like pentraxin-3." (PMID 40299527, 2025). "Due to significant discrepancies between published works, it is difficult to clearly confirm the direction of action of PTX3 in gastric cancer." (PMID 38136377, 2023). "Another study showed that PTX3 expression was increased in gastric cancer tissues and promoted tumor cell migration and macrophage recruitment, leading to gastric cancer-related inflammation." (PMID 33952272, 2021). "Here, we investigated the role of PTX3 in TAMs polarization and stemness in gastric cancer (GC), and further explored the effect of PTX3 on milky spot metastasis of gastric cancer." (PMID 34149932, 2021). "In order to explain the role of TNF-α on PTX3 in the migration as well as invasion of gastric cancer cells, we performed transwell assays." (PMID 32194791, 2020). "To identify the mechanism of PTX3 on the process of EMT of gastric cancer cells mediated by TNF-α, we examined typical EMT markers by western blot." (PMID 32194791, 2020). "Here, we inspected the expression of PTX3 in gastric carcinoma tissues along with gastric cell lines and established that PTX3 was suggestively inferior in gastric cancer tissue and cells." (PMID 32194791, 2020). "In brief, these outcomes recommend that PTX3 is unusually less expressed in human gastric cancer patients as well as cell lines." (PMID 32194791, 2020). "Conversely, overexpression of PTX3 inhibited progress both in vitro as well as in vivo in gastric cancer mediated by TNF-α." (PMID 32194791, 2020). "We established that upregulation of PTX3 noticeably reduced the gastric carcinoma migration and invasion capacity mediated by TNF-α." (PMID 32194791, 2020). "Recent studies have also indicated that gastric cancer-derived PTX3 promotes tumor cell migration and macrophage recruitment, thus contributing to gastric cancer-related inflammation." (PMID 28489600, 2017).
gastric cancer (continued). "BDNF acting via TrkB receptors increased the levels of long pentraxin 3 (PTX3) that was related to bone metastatic status of gastric cancer by enhancing gastric cancer–osteoblastic niche interactions." (PMID 27458153, 2016). "Second, TrkB activation by BDNF, produced by metastatic advanced gastric cancer cells, can induce PTX3 expression in the bone microenvironment, thereby contributing to an inflammatory osteoclastogenic condition by stimulating RANKL production from OBs." (PMID 27458153, 2016). "To verify the potential involvement of PTX3 in the BDNF-induced promotion of gastric cancer cell binding to OBs, we silenced PTX3 expression in HTB135 cells using PTX3-specific siRNA." (PMID 27458153, 2016). "Using IHC, we previously reported a general increase in PTX3 expression in patients with advanced gastric cancer with relapse-correlated metastasis." (PMID 27458153, 2016). "BDNF stimulates long pentraxin 3 (PTX3) expression through TrkB, thereby promoting interactions between bone metastatic gastric cancer cells and OBs and subsequent osteoclastogenesis." (PMID 27458153, 2016). "We next analyzed GEO (GSE27342 and GSE37023) to identify potential genes upregulated by TrkB and observed a positive correlation of TrkB expression with PTX3 in patients with gastric cancer (correlation coefficient=0.468, P <0.0001)." (PMID 27458153, 2016). "Silencing PTX3, in turn, reduced gastric cancer-related inflammation." (PMID 41479916, 2025). "It has been shown that PTX3 downregulation promotes gastric cancer migration and invasion." (PMID 36633805, 2023). "Therefore, the study conducted by Yeni and colleagues suggests a rather onco-suppressor activity of PTX-3 in gastric cancer, inconsistent with other studies." (PMID 36499628, 2022). "Overall, these results suggested that PTX3 could inhibit macrophage M2-like polarization and alleviate gastric carcinoma progression mediated by M2 macrophage." (PMID 34149932, 2021). "Here, we have demonstrated low manifestation of PTX3 in gastric cancer." (PMID 32194791, 2020). "We inspected the impacts of rhTNF-α on PTX3 in the gastric cancer cells." (PMID 32194791, 2020). "To examine the function of PTX3 in tumorigenesis, we inspected the gastric cancer database of TCGA to assess the differential manifestation of PTX3, which specified that cancer with PTX3 transcripts (n = 375) had suggestively lower manifestation level compare to normal samples (n =32)." (PMID 32194791, 2020). "Additionally, we compared the manifestation of PTX3 between the carcinoma tissue and paracancerous tissue in 50 patients, which showed that PTX3 was less expressed in gastric cancer tissues, and greatly expressed in normal tissues." (PMID 32194791, 2020). "Our study demonstrates the low expression of PTX3 in gastric samples and gastric cancer cell lines." (PMID 32194791, 2020). "Moreover, to authenticate the manifestation of PTX3 gene in gastric cancer, we used BGC-823, SGC-7901 as well as GES-1 cells, which got the same results." (PMID 32194791, 2020). "The findings that TrkB activation is an obligatory event in PTX3 expression and, in turn, that PTX3 stimulates TrkB expression clearly support the idea that PTX3 is a possible mediator in the bone metastatic gastric cancer–OB interaction with respect to the BDNF/TrkB axis." (PMID 27458153, 2016). "Given the associations of the PTX3 expression profile and its role in inflammation-mediated gastric cancer progression, it is reasonable to assume that PTX3 acts as a tumor promoter by enhancing inflammation rather than as a tumor suppressor, at least in metastatic advanced-stage gastric cancer." (PMID 27458153, 2016). "We next hypothesized that elevated PTX3 expression in bone metastatic HTB135 cells stimulates the interaction of bone metastatic gastric cancer cells with OBs." (PMID 27458153, 2016).